IL1B (interleukin 1 beta)
Diseases named in the same sentence as IL1B in open-access papers (continued):
Sharing a sentence is not in itself a finding about the gene and the disease.
Arthritis (continued). "In the present paper, we report that PBMCs of gout patients who have experienced attacks of arthritis produce more IL-1β than PBMCs of healthy volunteers when the cells are exposed to a combination of TLR2 ligands and MSU crystals." (PMID 22762240, 2012). "The results demonstrated that IL-17 was the first cytokine to peak (at 12 hours after arthritis induction), followed by IL-6, TNFα, IL-1β, and IFNγ at 24 hours after the challenge." (PMID 22676339, 2012). "IL-1β administration accelerated arthritis, while anti-IL-1β treatment markedly suppressed established arthritis." (PMID 22537858, 2012). "Recombinant IL-12, IFN-γ and IL-1β administration restored arthritis, but reduced joint TGF-β levels in TLR4-/- mice." (PMID 23036692, 2012). "As early as 7 hours after arthritis induction, the amounts of the proinflammatory cytokines IL-1β and IL-6 increased by 12- and 55-fold, respectively, in the SF of sensitized joints." (PMID 22414623, 2012). "In fact, we previously reported that the administration of E-64-d ameliorates the arthritis in CAIA mice via decreased IL-1β and IL-6 production in synovial cells." (PMID 22046434, 2011). "TNF-α and IL-1β are two inflammatory cytokines that are well defined as critical inflammatory mediators in arthritis." (PMID 21835002, 2011). "An IL-1β/IL-17 axis has been reported in experimental autoimmune encephalomyelitis and arthritis for which a crucial role for IL-1β in the induction of IL-17-producing T cells was demonstrated." (PMID 21858022, 2011). "Instead, the presence of other pro-inflammatory cytokines, such as IL-1β, was sufficient to generate arthritis, leaving IL-17RA signaling as an amplifier of serum-induced arthritis rather than an absolutely required mediator." (PMID 22028860, 2011). "IL-1β expression in the joint has previously been shown to be essential for the development of serum-induced arthritis with neutrophils as a major source for this cytokine." (PMID 22028860, 2011). "We also examined the effect of HLXL on two of the major arthritis-related cytokines (IL-1β and TNF-α) produced by the synovial tissue from the joints of arthritic mice and rats." (PMID 20981317, 2011). "In this context, we have recently shown that MMP9 mediates hypernociception that developed during antigen-induced arthritis, a model in which IL-1β also plays a role." (PMID 20920345, 2010). "If the mouse has been previously primed with the antigen (as in the AIA model) or given a systemic stimulus such as IL-1β (as in the mBSA/IL-1 arthritis model), then arthritis develops in the injected joint." (PMID 20973954, 2010). "Many of the expected cytokines are raised during arthritis in this model, such as IL-1β, IL-10 and IL-6, however, unexpectedly both GM-CSF and TNFα remain low." (PMID 21073728, 2010). "Cytokine IL-1β, one of the signature cytokines of RA and a target of a commonly used RA therapeutic, is found shortly after arthritis induction and can be reduced upon dexamethasone treatment (*p < 0.05)." (PMID 21073728, 2010). "We have recently demonstrated an enhanced mRNA expression of IL-1β in the ARC of normally fed arthritic rats suggesting its role in arthritis-induced cachexia." (PMID 20953376, 2010). "Previous studies from our laboratory have shown that green tea inhibited the development of arthritis in a mouse model and also inhibited the production of various inflammatory mediators by human chondrocytes stimulated with IL-1β." (PMID 19445683, 2009). "TNF and IL-1β, pivotal cytokines in arthritis pathogenesis, both have the ability to induce the release of HMGB1 from myeloid and dendritic cells." (PMID 18346273, 2008). "As we focus on the prevention and treatment of arthritis by natural products, in a previous report we showed that pomegranate extract was effective in suppressing the IL-1β-induced human cartilage matrix proteoglycan release in vitro." (PMID 18554383, 2008).
Arthritis (continued). "ACZ885, a novel human monoclonal antibody directed against human IL-1β, was found to be highly active in inhibiting IL-1β mediated arthritis in a preclinical animal model." (PMID 18534016, 2008). "Overall, our results indicate that PARP-1 plays a role in arthritis progression, probably through impaired IL-1β and MCP-1 production in joints." (PMID 16356201, 2006). "Activity of arthritis was determined by routine parameters for systemic inflammation, by histological scoring of synovitis and by semiquantitative RT-PCR of IL-1β, TNF-α, stromelysin and collagenase I in synovial tissue." (PMID 16542506, 2006). "IL-1β remained significantly increased in E/P-selectin mutant joint tissue during the early and chronic phases of arthritis." (PMID 16207337, 2005). "IL-1β was significantly elevated at the protein level from the induction of arthritis during the acute phase (days 1 and 3) until the beginning of the chronic phase of inflammation (day 7)." (PMID 15642138, 2005). "For example, van den Berg and coworkers showed that a combination of antibodies to IL-1α and IL-1β given before the onset of arthritis completely prevented murine CIA." (PMID 16207337, 2005). "Similarly, mice with antigen-induced arthritis showed severe joint inflammation and increased expression of IL-1β and NLRP3 inflammasome in the synovial membrane." (PMID 40732305, 2025). "Similarly, it was demonstrated that 0.5% CLA (c9,t11) reduced arthritis symptoms through the reduction of IL-6 and IL-1β levels in mice comparable to a 1.5 mg/kg dose of celecoxib." (PMID 40806004, 2025). "Pro-inflammatory cytokines (tumor necrosis factor-alpha [TNF-α], interleukin [IL]-6, IL-1β), antibodies (immunoglobulin [Ig]G, IgE), cyclooxygenase-2 (COX-2) enzyme activity, paw edema, and arthritis indices were measured using enzyme-linked immunosorbent assay and standard methods." (PMID 40342737, 2025). "Indeed, PARP1 and HOXA1 have been reported as key molecules in IL‐1β‐related inflammatory osteolysis and chondrocyte degradation, respectively, in human diseases such as arthritis." (PMID 40545975, 2025). "Decreased expression of RANKL and IL-6, increased number of T cells and the expression of IL-1β in KO mice; IL-17 deficiency did not affect arthritis severity." (PMID 40248692, 2025). "The finding of elevated SAA in the liver by inflammatory arthritis, specifically by IL-6 and IL-1β, raised the intriguing hypothesis that with the presence of arthritis, the liver takes an active part in exacerbating disease progression by secreting SAA." (PMID 38426494, 2024). "In addition, 50, 100, and 400 mg/kg mangiferin inhibits mRNA expression of cytokine genes in the thymus and spleen of mice with induced-arthritis and lead to decreased serum levels of IL-1β, IL-6, TNF-α, and RANKL by downregulating NF-κB and activating ERK1/2." (PMID 38794160, 2024). "Moreover, it increased the pathological severity of IL-1β-induced arthritis in mice and accelerated the infiltration of macrophages in the affected joints." (PMID 38556552, 2024). "Another study found that a 5 mg/kg dose of TQ in rats lowered TNF-α and IL-1β levels in arthritis." (PMID 39459282, 2024). "We also showed that three inhibitors (PMB, chloroquine, and anti-CD11b antibody) of inflammasome activation in BMDM suppressed arthritis following cell infiltration into the inflamed synovium by attenuating IL-1β secretion in the paws of a CAIA model infected with A. actinomycetemcomitans." (PMID 39143049, 2024). "Additionally, we measured the levels of TNF-α, IL-1β, and IL-6 in the OA joint by ELISA measurements, which are known to be elevated with the onset of arthritis and correlate with its severity." (PMID 39076894, 2024). "Rather, the SAA/NFAT5 axis may require an initial priming of synovitis repeatedly secreting a high amount of IL-1β and/or IL-6 so as to establish a chronic form of arthritis." (PMID 38426494, 2024).
Arthritis (continued). "The heightened protein expression of TNFα and IL-1β in the DRG has been linked to increased excitability in nociceptive sensory neurons in animals experiencing chronic pain due to nerve injury, bone cancer, and arthritis." (PMID 38612414, 2024). "Considering that ORM2 was synthesized at markedly greater levels in the liver than in the affected joints of mice with IL-1β-induced arthritis, a local form of chronic arthritis, we suspect that liver-derived ORM2 could also participate in this process." (PMID 38556552, 2024). "Interestingly, increased production of IL1-β and TNFα has been reported in an Nfil3−/− arthritis model." (PMID 38412963, 2024). "SAA1 overexpression in the liver accelerates progression of mBSA/IL-1β–induced arthritis." (PMID 38426494, 2024). "Considering that IL-1β is both an upstream and downstream gene of NF-κB, the present data indicate that baricitinib suppressed the IL-6 Amp, the amplification of these two pathways mediated by IL-6, during arthritis." (PMID 38879555, 2024). "Moreover, compared with vehicle injection, intra-articular injection of ORM2 markedly exacerbated the suboptimal severity of IL-1β-induced arthritis, as assessed by inflammatory cell infiltration and synovial hyperplasia." (PMID 38556552, 2024). "The overproduction of IL-1β has been observed in the spinal dorsal horn of animals with other pathological pain conditions, including neuropathic pain, inflammatory pain, arthritis, bone cancer pain, and chemotherapy (like paclitaxel)-induced chronic pain." (PMID 38612414, 2024). "In addition, SIN improved arthritis in rats by inhibiting pro-inflammatory cytokines IL-1β and IL-6, inhibiting MMP-2/-9, and increasing TIMP-1/-3." (PMID 38276618, 2024). "It has also been reported that cytokine released from arthritis-affected joints, inparticular IL-1β, can stimulate the secretion of metalloproteinases (MMPs),especially MMP-2 and MMP-9, in endothelial and vascular smooth muscle cells, whichmay reduce the action of vasoconstrictor agonists." (PMID 38775546, 2024). "Therefore, the in vitro articular chondrocyte model of arthritis was established by treating chondrocytes with 10 μg/mL concentration of IL-1β." (PMID 37587519, 2023). "Similarly, recent literature reported that Nec-1 significantly reduced the levels of TNF-α, IL-1β, and IL-6 and reduced the severity of arthritis in rats." (PMID 37446099, 2023). "AT-RvD1 caused pronounced and long-lasting analgesic effects in a model of adjuvant-induced arthritis in rats through inhibition of proinflammatory and pronociceptive mediators, including IL-1β, and through the blockage of COX-2 mRNA expression and NF-kB activation." (PMID 36903662, 2023). "Apart from TGF-β, LIF can also be induced by IL-1β during arthritis, which could account for these differences." (PMID 36850003, 2023). "Furthermore, Kat2a expression was strongly correlated with Il1b expression in synovial macrophages and clinical score of arthritis mice." (PMID 37313329, 2023). "Using two independent transgenic mouse arthritis models, either TNF‐ or IL‐1β dependent, we demonstrate that arthritis develops independently of the microbiota and intestinal inflammation, since both lines develop full‐blown articular inflammation under germ‐free conditions." (PMID 37694693, 2023). "As a pro‐inflammatory cytokine, IL‐1β plays a key role in the pathogenesis of arthritis." (PMID 37904715, 2023). "Together, these data indicate that also in this transgenic mouse model of innate (IL‐1β)‐driven arthritis, no causative role for the intestinal microbiota can be observed, as GF A20myel‐KO mice still develop severe arthritis." (PMID 37694693, 2023). "Our data demonstrated that nanoandaliman at low dose (25 mg/kg bw) showed a significant effect on suppressing the expression of cox-2, il-1b, inos, and mmp1 genes, indicating its potency as an anti-arthritic and anti-inflammatory agent for the management of arthritis." (PMID 36429168, 2022).
Arthritis (continued). "In vivo, BHA alleviated paw and joint swelling, decreased inflammatory cell infiltration in paw tissues, suppressed gene expressions of p38 and p65, down-regulated the NF-κB and MAPK signaling pathways and reduced protein levels of TNFα, IL-1β and IL-6 in joint tissues of arthritis rats." (PMID 35630747, 2022). "Furthermore, in vivo studies also showed that PR3 and elastase can compensate caspase-1 absence for pro-IL-1β processing both in a serum transfer–induced arthritis model and in the monosodium urate monohydrate crystal–induced peritonitis model." (PMID 36091026, 2022). "IL-1β has been known to play vital role in cartilage destruction in arthritis by mediating various pro-inflammatory mediators of inflammation, and is used to simulate arthritis in vitro." (PMID 36188601, 2022). "Likewise, D-carvone presented anti-arthritic activity against complete Freund’s adjuvant-induced arthritis in rats via significantly modulating the levels of inflammatory cytokines (IL-6, IL-1β, and TNF-α)." (PMID 36294936, 2022). "It was stated that the cytokines such as TNF-α, IL-1β, IL-6, IL-8, and IL-18 secreted by B lymphocytes and synovial fibroblasts (SFs) potentially regulate the balance of anti-inflammatory and pro-inflammatory factors during arthritis." (PMID 35877372, 2022). "Apart from IL-1β, also IL‐6 plays an arthritis- and inflammation-mediating role." (PMID 34142176, 2022). "Furthermore, when added to the diet of mice with collagen-induced experimental arthritis, linoleic acid was able to offset the damage, reducing joint edema, blood IL-1β levels, and hepatic arachidonic acid levels." (PMID 36364031, 2022). "In our experiment, LBP relieved the typical features of RA in rats, including the reduction of paw swell, arthritis scores and the contents of pro-inflammatory cytokines such as IL-1α, IL-1β, IL-12 and IL-17, and the recovery of the content of anti-inflammatory cytokine IL-10." (PMID 35864275, 2022). "IL-1β is another established biomarker of CHIKV arthritis severity in humans." (PMID 36377866, 2022). "Intraperitoneal administration of Fgl1 protein significantly decreased the inflammatory cytokine level (i.e., IL-1β and IL-6) in local paw tissue, and prevented joint inflammation, cellular infiltration, bone deformation and attenuated collagen-induced arthritis progression in vivo." (PMID 34975855, 2021). "Furthermore, we constructed an in vitro OA model by culturing chondrocytes in IL‐1β‐contained medium to mimic inflammation environment in arthritis." (PMID 34448527, 2021). "Indeed, we previously observed that recombinant IL‐38 suppresses IL‐1β in murine models of experimental arthritis." (PMID 33125159, 2021). "Among these mediators is the proinflammatory cytokine IL-1β, which is synthesized locally by synoviocytes and chondrocytes and has been shown to play a central role in the cartilage damage sustained in arthritis by creating an imbalance between cartilage degradation and repair processes." (PMID 34769349, 2021). "Treatment with L. casei or L. acidophilus over a period of 28 days reportedly prevented the development of arthritis in a preclinical model that reduced arthritic scores and proinflammatory cytokines such as IL-17, IL-1β, IL-6, and TNF-α, similar to that of indomethacin treatment." (PMID 34065638, 2021). "In addition, arthritis-associated factors, such as TNF-α, IL-1β, NF-κB transcription activity, prostaglandin E2, matrix metalloproteinases and COX-2 expression were inhibited by curcumin treatment." (PMID 34959384, 2021). "Therefore, controlling IL-1β-mediated inflammation is crucial for inhibiting arthritis-induced pathogenesis." (PMID 33567513, 2021). "The arthritis index, ankle joint swelling rate, IL-1β, IL-6, and MCP-1 levels in serum, SA level in liver tissue, and IκB, P-IκB, P65, and P-P65 protein levels in synovial tissues were significantly higher (P < 0.01) in the CIA model compared to the control group." (PMID 34367306, 2021).
Arthritis (continued). "A possible second mechanism to explain our findings is that, like S100A8/A9, other factors that are present during arthritis development can induce IL-1β expression and regulate its activation and as such be sufficient to fully activate IL-1β in Il1rn−/−XS100a9−/− mice." (PMID 34412663, 2021). "Both IL-1β-induced synovitis and intra-articular lavage resulted in transient joint inflammation with elevations in synovial fluid TP, WBC count, and PGE2; however, increases in TNF-α and inflammatory chemokines CCL2, CCL3, CCL5, and CCL11 were predominantly restricted to synovitis joints only." (PMID 33980227, 2021). "It has been reported that arthritis-related genes of IL1β, IL6, and TNFα are expressed in the cartilage in AVNFH and could be potential biomarkers for AVNFH." (PMID 34305456, 2021). "IL‐38 binds to the IL‐36 receptor (IL‐1R6) and exhibits anti‐inflammatory properties, for example by reducing the Candida albicans induced T helper (Th) 17 response in peripheral blood mononuclear cells (PBMC) and by reducing inflammation, IL‐1β, and IL‐6 in murine models of arthritis." (PMID 33125159, 2021). "The PI3K and Akt signaling cascade mediates IL-1β expression during the progression of arthritis." (PMID 34560673, 2021). "IL-1β was chosen for the induction of synovitis as it induces a similar level of inflammation to equine synovial fluid as LPS and is a known contributor to the etiology of arthritis." (PMID 33980227, 2021). "Moreover, our preliminary study verified the cytokines (TNF-α, IL-1β) and inflammatory mediators (MMP-1, MMP-3) associated with joint inflammation in animal models." (PMID 34190191, 2021). "The therapeutic potential of Vx765 was illustrated not only by its inhibition of IL‐1β releases from human monocytes in vitro, but also by its effect in reducing the serum levels of IL‐1β and other clinical biomarkers in murine models of dermatitis, arthritis, and temporal lobe epilepsy." (PMID 32343048, 2020). "Therefore, NLRP3 inflammasome inhibitors, a new type of anti‐inflammatory drug candidate that is different from the directly blocking IL‐1β, promise to alleviate arthritis symptoms and limit gout flare." (PMID 32656909, 2020). "We next investigated the influence of arthritis on [Ca2+] and [Ca2+]ex-induced IL-1β secretion." (PMID 32843625, 2020). "Notably, GPR91-deficient mice display decreased macrophage activation and reduced IL-1β production during antigen-induced arthritis as well as decreased dendritic cell traffic and reduced differentiation of Th17 cells in the lymph nodes." (PMID 32362840, 2020). "Previous studies showed increase in arthritis severity when TNF-α works in synergy with IL-1β." (PMID 30691120, 2019). "The results of this study revealed the important role of effective dose of probiotics in reducing edema, hyperalgesia, serum levels of IL-1β, spinal p38MAPK activity; and increasing levels of MOR expression during different phases of arthritis caused by CFA adjuvant." (PMID 30719247, 2018). "Potentiation of Fas-induced apoptosis by CRABP2 silencing could be of clinical interest because it persisted in the presence of TNFα and IL1β, two pro-inflammatory stimuli that are present in arthritis and that increase RA FLS survival." (PMID 29880835, 2018). "Moreover, recombinant IL-1β (rIL-1β) administration into mice can induce arthritis, whereas arthritis development is arrested in IL-1R−/− mice." (PMID 30622982, 2018). "Therefore, inhibition of IL-1β during CFA-induced arthritis can exacerbate inflammatory symptoms in the chronic phase by inhibiting the secretion of anti-inflammatory cytokines (Akhtari, Zaringhalam, Rohani, & Tekieh, 2013)." (PMID 30719247, 2018). "This study has shown that miR-146a KO mice suffer more severe gouty arthritis than WT mice and has indicated that miR-146a-deficient mice lose the repression of TRAF6 and IRAK1, leading to enhanced production and secretion of pro-IL-1β." (PMID 29544526, 2018).